ZCCHC4 (zinc finger CCHC-type containing 4)
Diseases named in the same sentence as ZCCHC4 in open-access papers:
ZCCHC4 is named in the same sentence as 20 diseases in open-access papers, as found by Europe PMC text mining. Sharing a sentence is not in itself a finding about the gene and the disease. The quoted sentences say what the papers report.
hepatocellular carcinoma (8 papers, 2021 to 2026). A malignant tumor that arises from hepatocytes. "Here, we report that zinc finger CCHC domain-containing protein 4 (ZCCHC4) is of aberrantly high expression in multiple human cancer tissues and is associated with poor prognosis and chemoresistance in patients of hepatocellular carcinoma (HCC), pancreatic cancer and colon cancer." (PMID 35853866, 2022). "Aberrantly expressed ZCCHC4 has been found to be correlated with poor prognosis and chemoresistance in various tumors, such as hepatocellular carcinoma, lung cancer and colorectal cancer." (PMID 39934309, 2025). "For instance, the RNA-binding protein ZCCHC4 (Zinc Finger CCHC-Type Containing 4) contributes to the development of chemoresistance in human hepatocellular carcinoma (HCC) by disrupting DNA-damage-triggered apoptosis." (PMID 40853971, 2025). "ZCCHC4 inhibits apoptotic signaling in hepatocellular carcinoma cells by interacting with lncRNA AL133467.2, thereby suppressing its pro-apoptotic function and thus promoting the chemoresistance to DNA-damaging agents (DDAs) in these cells." (PMID 40384875, 2025). "Moreover, hepatocellular carcinoma tumor tissues presented high levels of ZCCHC4 and m6A in 28S rRNA, indicating that ZCCHC4-mediated m6A methylation in 28S rRNA might play a general role in tumor growth and progression." (PMID 33946178, 2021). "For instance, the RBP ZCCHC4 suppresses DNA damage-induced apoptosis by interacting with the long non-coding RNA AL133467.2, thereby promoting chemoresistance in hepatocellular carcinoma cells." (PMID 40384875, 2025). "However, a study showed that the proliferation of ZCCHC4 KO HepG2 cells, derived from the liver tissue of a patient with hepatocellular carcinoma (HCC), was significantly inhibited, which was consistent with the defective translation of specific mRNAs in regulating tumorigenesis." (PMID 36446846, 2022).
colon cancer (2 papers, 2022 to 2025). "Previous studies have suggested that high ZCCHC4 levels are associated with liver cancer, colon cancer, small cell lung cancer." (PMID 39934309, 2025). "In addition to HCC, IHC analysis of TMA showed significantly higher expression of ZCCHC4 in pancreatic cancer (PC), colon cancer (CC), and lung cancer (LC) tissues compared to that in their paired non-tumor tissues." (PMID 35853866, 2022).
colorectal cancer (2 papers, 2024 to 2025). A primary or metastatic malignant neoplasm that affects the colon or rectum. "Our study first detected m6A levels in colorectal cancer tissues and further demonstrated that ZCCHC4 was a key factor in altering m6A levels, which made it possible to observe ZCCHC4, a newly identified methyltransferase from the perspective of m6A for the first time." (PMID 38326863, 2024).
liver cancer (2 papers, 2022 to 2025). An epithelial or non-epithelial malignant neoplasm that arises from the liver. "Meanwhile, upregulated ZCCHC4 expression was found to be associated with poor prognosis in liver cancer patients and to promote tumor growth and chemoresistance of HCC cells." (PMID 39934309, 2025).
lymph node metastasis (2 papers, 2024 to 2025). "Aberrant expression of ZCCHC4 is associated with cancer stages, lymph node metastasis (LNM), and tumor histology, and poorer Overall Survival (OS) in esophageal cancer." (PMID 39934309, 2025). "Statistical analysis of the clinical features showed that low expression of ZCCHC4 was positively correlated with good prognosis and lymph node metastasis." (PMID 38326863, 2024). "Notably, this heightened expression of ZCCHC4 is significantly correlated with TNM stages and lymph node metastasis, underscoring its potential clinical relevance." (PMID 39934309, 2025).
esophageal cancer (1 paper, 2025). A primary or metastatic malignant neoplasm involving the esophagus. "The study suggests a potential adjunctive role for ZCCHC4 in the diagnosis and treatment of esophageal cancer and aids in further understanding the underlying mechanisms in ESCA progression." (PMID 39934309, 2025). "The results suggested ZCCHC4 promotes proliferation, inhibits apoptosis, and increases cisplatin resistance in esophageal cancer cells." (PMID 39934309, 2025). "In summary, we demonstrate that knockdown of ZCCHC4 inhibits esophageal cancer progression and reduces cisplatin resistance in vivo." (PMID 39934309, 2025). "Conversely, overexpression of ZCCHC4 promotes proliferation, inhibits apoptosis, and increases resistance to cisplatin in esophageal cancer cells." (PMID 39934309, 2025). "Flow cytometry analysis showed an augmentation in ROS production in esophageal cancer cells with ZCCHC4 knockdown." (PMID 39934309, 2025). "Conversely, ZCCHC4 over-expression promotes proliferation, inhibits apoptosis, and increases cisplatin resistance in esophageal cancer cells." (PMID 39934309, 2025). "The mRNA level of ZCCHC4 in esophageal cancer patients correlates with serum carcinoembryonic antigen (CEA) levels, Squamous Cell Carcinoma (SCC) markers, and tissue polypeptide antigen (TPA) levels." (PMID 39934309, 2025). "From a functional perspective, we demonstrated that downregulation of ZCCHC4 inhibits proliferation, promotes apoptosis in esophageal cancer, and also enhancing sensitivity to cisplatin treatment." (PMID 39934309, 2025). "To further delve into the functional roles of ZCCHC4 in esophageal cancer, we used shRNA to knockdown ZCCHC4 and found that the expression of c-myc was also decreased, while the DNA damage marker p-H2A.X was significantly increased." (PMID 39934309, 2025). "To further explore the functional roles of ZCCHC4 in esophageal carcinoma, we employed the “Gene Set Variation Analysis” (GSVA) package to investigate the relevance of ZCCHC4 to hallmark sets within the context of ESCA." (PMID 39934309, 2025). "However, the expression and functional analysis of the role of ZCCHC4 in esophageal cancer (ESCA) is still elusive." (PMID 39934309, 2025). "The expression of ZCCHC4 in esophageal cancer tissues was evaluated by qPT-PCR and western blot." (PMID 39934309, 2025). "This concordance strengthens the hypothesis of a functional link between ZCCHC4 and the c-myc pathway in esophageal cancer." (PMID 39934309, 2025). "In summary, the present study elucidates the overexpression of ZCCHC4 in esophageal cancer, with a marked correlation observed between ZCCHC4 mRNA levels and clinicopathological features, suggesting a potential adjunctive role for ZCCHC4 in the diagnosis and prognosis of esophageal cancer." (PMID 39934309, 2025). "Knockdown of ZCCHC4 induces DNA damage, leading to an elevation of reactive oxygen species (ROS), which in turn triggers S-phase arrest, enhances apoptosis, augments sensitivity to cisplatin treatment, and inhibits proliferation in esophageal cancer cells." (PMID 39934309, 2025). "Additionally, downregulation of ZCCHC4 inhibits the progression of esophageal cancer and reduces cisplatin resistance in vivo." (PMID 39934309, 2025). "Furthermore, scavenging ROS reverses the effects of ZCCHC4 downregulation on both proliferation and apoptosis in esophageal cancer cells." (PMID 39934309, 2025). "Furthermore, downregulation of ZCCHC4 increases sensitivity to cisplatin treatment, promotes apoptosis, and inhibits proliferation of esophageal cancer cells, potentially through the ROS/c-myc axis." (PMID 39934309, 2025). "Consequently, further identification of specific ZCCHC4 inhibitors holds direct translational significance for the treatment of esophageal cancer in the future." (PMID 39934309, 2025).
esophageal cancer (continued). "Since our findings indicate that ZCCHC4 promotes the proliferation of esophageal cancer cells and enhances cisplatin resistance, we investigated whether knockdown of ZCCHC4 inhibits the progression of esophageal cancer and increases sensitivity to cisplatin in vivo." (PMID 39934309, 2025). "Moreover, higher expression level of ZCCHC4 had the poorer OS rate in esophageal cancer patients." (PMID 39934309, 2025). "Downregulation of ZCCHC4 leads to increased sensitivity of ESCC cells to cisplatin, and inhibits the proliferation and promotes apoptosis of esophageal cancer cells, potentially via the ROS/c-myc axis." (PMID 39934309, 2025). "In summary, downregulation of ZCCHC4 leads to increased sensitivity of ESCC cells to cisplatin, inhibits proliferation, and promotes apoptosis in esophageal cancer cells, potentially via the ROS/c-myc axis." (PMID 39934309, 2025). "Next, downregulation of ZCCHC4 leads to increased sensitivity of ESCC cells to cisplatin, suppression of cell viability, a reduction in the S phase of the cell cycle, and the induction of apoptosis in esophageal cancer cells." (PMID 39934309, 2025).
esophageal squamous cell carcinoma (1 paper, 2025). Esophageal squamous cell carcinoma (ESCC) is a type of esophageal carcinoma (EC) that can affect any part of the esophagus, but is usually located in the upper or middle third. "Relationship between ZCCHC4 expression and pathway enrichment analysis were analyzed by R. The reactive oxygen species (ROS), cell proliferation, cell cycle and apoptosis of ZCCHC4 in esophageal squamous cell carcinoma (ESCC) cells tested by CCK8 assay and flow cytometry assay." (PMID 39934309, 2025).
esophageal tumor (1 paper, 2025). "Furthermore, the mRNA levels of ZCCHC4 exhibit an association with serum esophageal tumor markers in patients, hinting at its potential utility in diagnostic and prognostic contexts." (PMID 39934309, 2025).
inflammatory bowel disease (1 paper, 2023). A spectrum of small and large bowel inflammatory diseases of unknown etiology. "For m6A writer, zinc finger CCHC domain-containing protein 4 (also known as ZCCHC4) is mainly involved in 28S rRNA methylation and relevant to the fate of core cytokines in inflammatory bowel diseases." (PMID 37434186, 2023).
osteosarcoma (1 paper, 2025). A usually aggressive malignant bone-forming mesenchymal neoplasm, predominantly affecting adolescents and young adults. "Studies have shown that Zinc finger CCHC-type containing 4 (ZCCHC4) upregulates integrin β1 (ITGB1) to promote osteosarcoma progression." (PMID 40585991, 2025).
pulpitis (1 paper, 2023). Inflammation of the dental pulp. "However, YTHDF1, YTHDF3, METTL16 and METTL3 gene expression were not statistically different between the pulpitis group and the control group, and RBM15B, ZCCHC4 and ALKBH5 were up-regulated." (PMID 37978362, 2023).
tumor (14 papers, 2020 to 2025). "In this study, we investigated the expression of ZCCHC4 mRNA and protein, which was higher in cancer tissues and significantly associated with cancer stages, nodal metastasis status, and tumor markers." (PMID 39934309, 2025). "HCC cell deficiency of ZCCHC4 reduces tumor growth in vivo and intratumoral interference of ZCCHC4 expression obviously enhances the DDA-induced antitumor effect." (PMID 35853866, 2022). "Next, the relationship between ZCCHC4 levels and clinical pathological characteristics is explored, higher mRNA level of ZCCHC4 was significantly associated with lymph node metastasis statuses N0, N2, N3, and N4, cancer stages 1–4 and tumor histology." (PMID 39934309, 2025). "Nineteen genes (44%) demonstrated loss or promoter silencing of the wildtype allele in at least one tumour, with six genes (SLC12A4, LOXL2, ZCCHC4, LLGL2, MIPOL1, SCYL3) demonstrating this in multiple samples." (PMID 39794353, 2025). "Consistent with in vitro findings, mice with subcutaneous tumors derived from ESCC cells in which ZCCHC4 was knocked down exhibited significantly inhibited tumor growth, as well as reduced tumor volume and weight following treatment with cisplatin." (PMID 39934309, 2025). "IHC results showed that ZCCHC4 was highly expressed in the tumor tissues of 175 patients, while patients with low expression accounted for only 26.47%." (PMID 38326863, 2024). "Subcutaneous tumor-bearing experiments in mice also confirmed that the ZCCHC4 knockout inhibited CRC progression." (PMID 38326863, 2024). "Accordingly, less cell death and decreased levels of cleaved caspase 3 in tumor tissues of mice bearing ZCCHC4 OE cells were observed." (PMID 35853866, 2022). "Consistently, the immunohistochemistry (IHC) analysis showed that the protein level of ZCCHC4 was significantly higher in HCC tissues, with 73% (47/64) of HCC tissues showing increased ZCCHC4 expression compared to corresponding non-tumor tissues." (PMID 35853866, 2022). "We found that the combined treatment of ZCCHC4-siRNA plus OXA exhibited the most significant antitumor effects, accompanied with the most significantly reduced tumor growth, compared with in vivo administration of siRNA targeting ZCCHC4 alone or OXA alone." (PMID 35853866, 2022). "Then, we subcutaneously injected ZCCHC4 KO cells and wild-type HepG2 cells (WT cells) into nude mice and found that mice bearing ZCCHC4 KO cells displayed slower tumor growth and longer overall survival." (PMID 35853866, 2022). "When testing the expression levels of γH2AX in tumor tissues of mice receiving combined use of ZCCHC4-siRNA and OXA, we found that combo-treatment markedly increased phosphorylation levels of H2AX in tumors." (PMID 35853866, 2022). "We found that the mRNA expression of ZCCHC4 was higher in HCC tissues as compared to non-tumor tissues, and the higher expression of ZCCHC4 in HCC tissues predicted shorter overall survival and disease-free survival." (PMID 35853866, 2022). "The present findings offer compelling evidence that ZCCHC4 emerges as a promising candidate biomarker, complementary to established tumor markers, and may contribute to a more comprehensive molecular profiling strategy for ESCC diagnosis and prognosis." (PMID 39934309, 2025). "Therefore, we further analyzed the correlation between the expression level of ZCCHC4 and tumor markers, the findings presented a compelling correlation between the mRNA expression levels of ZCCHC4 and a panel of tumor biomarkers, including CEA, SCC, TPA." (PMID 39934309, 2025). "DNA damage induces the generation of ROS14, and elevated levels of reactive oxygen species (ROS) can impede tumor progression by suppressing c-myc15, leading us to hypothesize that ZCCHC4 may regulate c-myc expression downregulation via ROS modulation." (PMID 39934309, 2025).
tumor (continued). "IHC results showed a decrease in the molecular marker Ki-67 for cell proliferation in ZCCHC4 deficient tumors compared to overexpression group, suggesting that ZCCHC4 may be a driving factor for CRC tumor development." (PMID 38326863, 2024). "We found that OXA treatment could significantly inhibit tumor growth in mice bearing mock cells rather than mice bearing ZCCHC4 OE cells, and overexpression of ZCCHC4 could attenuate OXA-induced tumor growth in vivo." (PMID 35853866, 2022). "We found a previously unidentified role of ZCCHC4 in tumor chemoresistance, in a manner dependent on inhibition of DNA-damage-induced apoptosis, and that targeting ZCCHC4 could increase chemosensitivity of HCC." (PMID 35853866, 2022). "In addition to regulating tumor cell apoptosis, whether ZCCHC4 also plays a role in the crosstalk between tumor cells and immune cells in the microenvironment is an intriguing issue to be addressed in the future." (PMID 35853866, 2022). "Meanwhile, we detected the ZCCHC4 protein levels in 41 pairs of ESCC tissues, and 30 cases of tumor tissues showed significantly over-expression." (PMID 39934309, 2025). "It is worth noting that the high expression group of ZCCHC4 showed increased growth ability of CRC cells in nude mice, resulting in more volume, as confirmed by in vivo imaging, increased tumor weight and poor prognosis." (PMID 38326863, 2024). "The ZCCHC4 protein is overexpressed in HCC tumours, and ZCCHC4 knockout was found to significantly reduce the tumour size in mouse xenograft models." (PMID 34246319, 2021). "Another new m6A methyltransferase, ZCCHC4, was overexpressed in HCC, and ZCCHC4 knockout eliminated m6A modification of 28S rRNA, inhibited HepG2 cell proliferation and reduced the tumor size in a xenograft mouse model." (PMID 34692544, 2021). "In terms of mechanism, ZCCHC4 inhibits the apoptosis of CRC cells by interacting with a long-chain non-coding RNA (lncRNA) and promotes the proliferation, migration, and invasion of tumor cells." (PMID 38326863, 2024). "Thus, ZCCHC4 promotes tumor growth of HCC in vivo, indicating that ZCCHC4 is pro-tumorigenic in HCC." (PMID 35853866, 2022). "The results of this study suggest that ZCCHC4 is abnormally highly expressed in various digestive tract tumor tissues and may be a key regulator of CRC progression, and its knockdown can significantly inhibit tumor progression." (PMID 38326863, 2024). "Also, the detailed signaling pathways influenced by ZCCHC4 in modulating tumor development and therapeutic response are not addressed." (PMID 35853866, 2022). "However, we found YTHDC1, ZCCHC4, IGF2BP1 were not differently expressed between normal and tumor samples." (PMID 33748145, 2021).
cancer (6 papers, 2020 to 2026). A tumor composed of atypical neoplastic, often pleomorphic cells that invade other tissues. "The transcriptional expression of ZCCHC4 in different cancers was explored using the TIMER database, ZCCHC4 mRNA expression was significantly upregulated in ESCA patients." (PMID 39934309, 2025). "Here, we revealed an important role for a rarely studied RBP--ZCCHC4 in promoting HCC chemoresistance, and identified ZCCHC4 as a new predictor of cancer poor prognosis and a potential target for improving chemotherapy effects in cancer patients." (PMID 35853866, 2022). "In the current study, we comprehensively investigated the biological role of ZCCHC4 in human cancer and revealed that ZCCHC4 could predict the poor prognosis and impede chemotherapy responsiveness of cancer patients with different cancer types." (PMID 35853866, 2022). "Together, our study identifies ZCCHC4 as a new predictor of cancer poor prognosis and a potential target for improving chemotherapy effects, providing mechanistic insights to the roles of RBPs and their partners in cancer progression and chemoresistance." (PMID 35853866, 2022). "In conclusion, our study identified ZCCHC4 as a novel predictor of poor prognosis in CRC and a potential treatment target, providing mechanistic insights into its role in cancer progression." (PMID 38326863, 2024). "Our findings identify ZCCHC4 as a potential target to improve the chemotherapy effects, and provide insight into the role of RBP-RNA network in cancer progression." (PMID 35853866, 2022). "Thus, ZCCHC4 may play an important role in multiple cancer types." (PMID 35853866, 2022). "ZCCHC4 was finally recognized because of its role as a member of the RBP family, which has been shown to play an important role in the development and treatment of cancer." (PMID 38326863, 2024). "Moreover, we demonstrated that the interaction of ZCCHC4 with previously uncharacterized lncRNA AL133467.2 and DNA-damage indicator γH2AX inhibited DNA-damage-induced apoptosis in HCC cells, thus adding new insight to the roles of RBPs in cancer development and chemoresistance." (PMID 35853866, 2022).
ZCCHC4 also shares sentences with these, for which no sentence is quoted: breast carcinoma (2 papers); lung carcinoma (2); breast tumors (1); cannabis dependence (1); COVID-19 (1); pancreatic cancer (1); squamous cell carcinoma (1).